SELE (selectin E)
Diseases named in the same sentence as SELE in open-access papers (continued):
Sharing a sentence is not in itself a finding about the gene and the disease.
colon carcinoma (44 papers, 2008 to 2025). "Several studies have shown that altered E-selectin expression on activated endothelial cells greatly influences metastasis formation and subsequent colonization, and increased circulating E-selectin levels have been associated with metastasis of both breast and colon carcinoma cells to the liver." (PMID 26407999, 2015). "The activation of ERK by E-selectin enhances the extravasation and transendothelial migration of colon cancer cells by activating Src kinase and dissociating the VE-cadherin/beta-catenin complex." (PMID 36497322, 2022). "For example, IL-1β induces E-selectin-dependent extravasation of colon cancer cells, and subsequently regulating E-selectin expression by modulating miR-31 transcription." (PMID 33406733, 2021). "The pH and glucose-activated cellular internalization of SPCS/C6 micelles was examined by inverted fluorescence microscope in a colon cancer Caco2 cell line with E-selectin expressing on the cell membrane." (PMID 34138187, 2020). "Taken all together, these results suggest that miR-146a and miR-181b are important modulators of the metastatic processes of colon cancer cells by regulating E-selectin expression." (PMID 29402939, 2018). "Adhesion of colon cancer cells to E-selectin expressing endothelial cells is a prerequisite to their transendothelial migration (TEM) during metastatic dissemination." (PMID 29402939, 2018). "Colon cancer cell clones showed a direct correlation between ability to bind to E-selectin expressing ECs and metastatic potential, while a subpopulation of colon cancer cells initiated the process of diapedesis after adhering to activated HUVECs expressing E-selectin." (PMID 24386459, 2013). "The selectin E gene (SELE) was predicted to be downstream regulated by NFκB via such chemokines (CCL8, CXCL2, CXCL3), while previous studies observed that it activates the PI3K/NFκB pathway in colon cancer." (PMID 27078000, 2016). "Cimetidine, which inhibits the induction of E-selectin expression, significantly decreased liver metastasis of HT-29 colon cancer cells in an athymic mouse model without affecting the primary tumor." (PMID 24386459, 2013).
Hypertension (38 papers, 2007 to 2025). The presence of chronic increased pressure in the systemic arterial system. "Qin L., Zhao P., Liu Z., Chang P. Associations SELE gene haplotypevariant and hypertension in Mongolian and Han populations.Intern Med." (PMID 40144370, 2025). "Meta-analysis suggests that carriers of the C allele of the A561C polymorphism of the SELE gene may contribute to an increased risk of hypertension in the Chinese Han population." (PMID 35194526, 2022). "The data indicated that several DEGs, including prostaglandin I2 (prostacyclin) synthase (PTGIS), RGS5, selectin E (SELE), endothelin converting enzyme (ECE), and ATPase, Na+/K+ transporting, and beta 1 polypeptide (ATP1B1), were highly associated with hypertensive disease." (PMID 32041970, 2020). "IL-1β in essential hypertension enhances VCAM-1, ICAM-1, and E-selectin expression with atherosclerotic effects." (PMID 31186952, 2019).
coronary artery disease (34 papers, 2006 to 2025). "SELE polymorphisms (A561C) and (G98T) were also found to be strongly related to an elevated risk of coronary heart disease." (PMID 36617649, 2022). "There are other studies that support this finding stating how selectin-E is higher in stable and lower grade stenosis in patients with coronary heart disease." (PMID 40821632, 2025). "Observational studies have shown that elevated levels of SELE have been observed in acute myocardial infarction, coronary heart disease, restenosis following peripheral arterial angioplasty, and stable and unstable angina." (PMID 24260191, 2013). "E-selectin (SELE) mediates the rolling and adhesion of leukocytes on activated endothelial cells and plays a critial role in the pathogenesis of coronary artery disease (CAD)." (PMID 24260191, 2013).
Obesity (34 papers, 2007 to 2025). Accumulation of substantial excess body fat. "The pre-test results in this study also indicate an approximately 30% difference in expression when VSG, OG, and NG were compared, which implies that the regulation of E-selectin expression is important in both obesity and vascular stiffness." (PMID 37834763, 2023). "Another study of 150 participants (100 with obesity and 50 without obesity) in the Netherlands found that SELE, IGFBP1 and RARRES2 were significantly different between participants with obesity versus without obesity." (PMID 38548792, 2024).
ischemic stroke (28 papers, 2011 to 2024). A stroke disorder caused by obstruction of blood flow to the brain, due to thrombotic (local blood clot formation) or embolic (due to a blood clot or other material traveling from another site) event. "Recently, results from a meta-analysis reported that the SELE gene A561C polymorphism was significantly associated with susceptibility to ischemic stroke, which results from cerebrovascular atherosclerosis." (PMID 24260191, 2013). "Moreover, it abolished the inhibitory effect of 0.7 g/kg/day ethanol on ICAM-1 and E-selectin expression under physiological conditions and following ischemic stroke." (PMID 39682755, 2024).
leukemia (22 papers, 2012 to 2026). A malignant (clonal) hematologic disorder, involving hematopoietic stem cells and characterized by the presence of primitive or atypical myeloid or lymphoid cells in the bone marrow and the blood. "This association between leukemia status and E-selectin expression was also observed on BMECs from the AML model." (PMID 38643279, 2024). "GMI-1271 (Uproleselan), an E-selectin antagonist, is intended to inhibit E-selectin expression on endothelial cells so that E-selectin-mediated drug resistance in leukemia can be prevented." (PMID 33425742, 2020). "This same group used in vivo confocal imaging to demonstrate that leukemia cells preferentially home to unique E-selectin expressing ECs." (PMID 23560111, 2013). "Additionally, we found that significantly more leukemia cells adhere to secondary activated ECs, presumably due to the higher levels of activation and E-selectin expression." (PMID 23560111, 2013). "However, addition of KG-1 cells or TNF-α to culture significantly increased E-selectin expression demonstrating that primary ECs can be activated by leukemia cells." (PMID 23560111, 2013).
acute myeloid leukemia (18 papers, 2016 to 2025). Acute myeloid leukemia (AML) is a group of neoplasms arising from precursor cells committed to the myeloid cell-line differentiation. "Using acute myeloid leukemia (AML) mouse models, we show AML blasts release inflammatory mediators that upregulate endothelial niche E-selectin expression." (PMID 32341362, 2020).
prostate carcinoma (17 papers, 2012 to 2025). A carcinoma that arises from epithelial cells of the prostate gland. "CTCs from prostate cancer patients tethered and interacted with E-selectin and E-selectin expressing HUVECs." (PMID 39459070, 2024). "As CXCL1 and CXCL2 were predicted as downstream targets of NFκB in prostate cancer, we suggest SELE as another important downstream target in this process." (PMID 27078000, 2016). "Our predicted NFκB pathway suggested 8 novel genes which were found to be highly down-regulated in lethal prostate cancer and highly functionally related to NFκB, namely ATF3, CXCL2, DUSP5, JUNB, NEDD9, SELE, TRIB1, and ZFP36." (PMID 27078000, 2016). "Notable genes in the predicted pathway included ATF3, JUNB, KLF6, NR4A2, ZFP36, DUSP5 and NEDD9, as well as STAT3 and IRF1 as novel upstream regulators, and SELE, CXCL1 and CXCL2 as novel downstream targets of NFκB in prostate cancer." (PMID 27078000, 2016). "E-selectin enabled the liposomes to bind to E-selectin ligands widely expressed by leukocytes as well as CTCs and to eliminate the CTCs via TRAIL-induced apoptosis thus preventing prostate cancer metastasis." (PMID 36291908, 2022).
rheumatoid arthritis (17 papers, 2010 to 2023). A chronic, systemic autoimmune disorder characterized by inflammation in the synovial membranes and articular surfaces. "Furthermore, a high level of circulating E-selectin is also correlated with other inflammatory diseases, including rheumatoid arthritis, Grave’s disease, and systemic vasculitis, indicating the importance of the SELE gene in inducing inflammation." (PMID 36983834, 2023). "Consequently, elevated E-selectin expression was reported in many types of inflammatory diseases including diabetes, atherosclerosis, rheumatoid arthritis, and cancer." (PMID 20927342, 2010).
melanoma (16 papers, 2008 to 2025). A malignant, usually aggressive tumor composed of atypical, neoplastic melanocytes. "Taken together, these data indicate that SSeCKS/AKAP12 suppresses melanoma adhesion to endothelial cells based on reduction of E-Selectin expression." (PMID 30323895, 2018). "Additionally, Ang II/AT1R promotes pulmonary metastasis in melanoma by increasing E-selectin expression, helping in the adherence of melanoma cells to the lung during the endothelium adhesion stage of metastasis process." (PMID 34539580, 2021).
psoriasis (16 papers, 2013 to 2025). An autoimmune condition characterized by red, well-delineated plaques with silvery scales that are usually on the extensor surfaces and scalp. "Methotrexate (MTX) is used to treat psoriasis, and one of its main mechanisms of action is believed to be based on its effect of decreasing E-selectin expression." (PMID 32942670, 2020). "The essential mechanism of action of MTX in psoriasis might relate to a decrease in E-selectin expression during treatment." (PMID 32942670, 2020).
pancreatic cancer (14 papers, 2010 to 2023). "Hepatic ischemia-reperfusion increases liver metastases and E-selectin expression in pancreatic cancer." (PMID 22766603, 2012).
ischemia (13 papers, 2010 to 2025). A hypoperfusion of the BLOOD through an organ or tissue caused by a PATHOLOGIC CONSTRICTION or obstruction of its BLOOD VESSELS, or an absence of BLOOD CIRCULATION. "Previous studies revealed that HGF can inhibit neutrophil infiltration via the downregulation of Selectin-E on the endothelial cell surface, which suppresses ischemia-related injury in various organs." (PMID 32680554, 2020). "E-selectin expression was also measured in samples of brain ipsilateral and contralateral to the ischemia." (PMID 20122276, 2010).
type 1 diabetes (12 papers, 2012 to 2024). "In addition, SELE was reported as an inflammatory marker, and played a role in kidney dysfunction with type 1 diabetes, which was overexpressed in the endothelial cells in HBV-associated MN patients." (PMID 35935760, 2022).
viral infection (12 papers, 2010 to 2024). "High lymphocyte infiltration in virus-positive tumors may reflect both enhanced antigenicity associated with viral infection and virus-independent factors, such as E-selectin expression on vascular endothelium that promotes lymphocyte egress." (PMID 25950432, 2015). "Down-regulation of IL15, NOS2A, CCR4 and up-regulation of IL17, CYP7A1, SELE, IL5, RPL3L genes in both patient categories indicative of response to p-H1N1-09 virus infection." (PMID 20957032, 2010). "Retargeting virus with an isotype control antibody (IgGpcAdluc), did not restore viral infection in E-selectin-expressing cells." (PMID 20965218, 2011).
Arthritis (10 papers, 2005 to 2022). Inflammation of a joint. "Selectins are expressed in lymphoid, myeloid, and endothelial cells, and mice deficient in Selectin-P and selectin-E show an enhanced arthritis progression." (PMID 33879788, 2021). "This was validated in E-selectin-expressing endothelial cells, in which IKK complex assembly was inhibited in vitro and in vivo, resulting in the reduction of NF-κB activity specifically in E-selectin-expressing cells as well as the attenuation of experimental arthritis (STIA and AIA) in mice." (PMID 35336746, 2022).
Cerebral ischemia (10 papers, 2010 to 2023). Restriction of arterial blood supply to the brain associated with insufficient oxygenation to support the metabolic requirements of the tissue. "Following cerebral ischemia/reperfusion, TNF-α levels are increased within two hours, followed by a peak in P-selectin expression at 6 hours and a later peak in E-selectin expression between 6 and 12 hours." (PMID 20122276, 2010). "In contrast to its effects on the expression of ICAM-1 and VCAM-1 molecules that promote firm adhesion—iNO had no apparent effect on E-selectin or P-selectin expression following cerebral ischemia." (PMID 38102677, 2023).
gastric cancer (10 papers, 1997 to 2024). A primary or metastatic malignant neoplasm involving the stomach. "Except that SELE and KIT are not being studied in depth right now, we found several genes that were related to the prognosis and survival of gastric cancer patients." (PMID 34367971, 2021).
colorectal cancer (9 papers, 1998 to 2025). A primary or metastatic malignant neoplasm that affects the colon or rectum. "Furthermore, in Malaysians, the SELE S128R gene polymorphism has been related to BC, as well as linked to a higher risk of relapse and death in colorectal cancer patients." (PMID 36617649, 2022). "Selectin-E (SELE) levels are significantly higher in colorectal cancer cells in comparison to adjacent healthy cells." (PMID 39839775, 2024). "Protein quantitative trait loci analyze studies provided further evidence for the involvement of TFF1, CEACAM5, and SELE in colorectal cancer, with possible connections to the PI3K/Akt and MAPK signaling pathways." (PMID 39839775, 2024). "TFF3, TFF1, SELE, AHCY, LCN2, CEACAM5, and RETN are consistently upregulated across a variety of datasets and analyzes, which supports their crucial roles in the underlying mechanisms of colorectal cancer progression." (PMID 39839775, 2024). "Seven proteins namely TFF3, LCN2, CEACAM5, TFF1, SELE, RETN, and AHCY proteins of both phases were found to be upregulated in colorectal cancer in human protein atlas database, also were significant in our UK Biobank dataset and had an essential function in CRC." (PMID 39839775, 2024). "Seven proteins, TFF3, LCN2, CEACAM5, TFF1, SELE, RETN, and AHCY were found to be upregulated in other databases and also in our UK Biobank where TFF3 and LCN2 were found to be the most significant proteins and were highly expressed in colorectal cancer." (PMID 39839775, 2024).
vasculitis (9 papers, 2012 to 2025). "This is the first study to show that levels of E-selectin expression are significantly increased in lupus nephritis and vasculitis in MRL/lpr mice and that this effect is accompanied by increases in inflammatory cell infiltration." (PMID 25400916, 2013). "However, it remains controversial as to whether E-selectin expression contributes to the aggregation of CD8+T cells in kidneys affected by lupus nephritis and vasculitis." (PMID 25400916, 2013).
hepatocellular carcinoma (8 papers, 1997 to 2025). A malignant tumor that arises from hepatocytes. "For example, cimetidine and amiloride have shown anti-cancer effect through directly block E-selectin expression in hepatocellular carcinoma (HCC)." (PMID 39100681, 2024).
breast tumor (7 papers, 2008 to 2024). "We found substantial CD45+ immune cell density adjacent to E-selectin expressing inflamed vessels in doxorubicin (DOX)-treated residual human breast tumors." (PMID 32204492, 2020).
lupus (6 papers, 2013 to 2023). "We found significantly increased E-selectin expression in the glomeruli and renal interstitial microvasculature of MRL/MpJ-lpr/lpr (MRL/lpr) lupus model mice." (PMID 25400916, 2013).
malaria (6 papers, 2008 to 2024). Malaria is a serious and sometimes fatal disease caused by a parasite that commonly infects a certain type of mosquito which feeds on humans. "CD106 (also known as V-CAM1) as well as Selectin E (also known as CD62E) are cell adhesion molecules that are mainly found on endothelial cells and their EVs, and their reduction on sEVs in malaria patients indicates a lower release of sEVs from endothelial cells." (PMID 36961624, 2023).
endometriosis (5 papers, 2016 to 2023). The growth of functional endometrial tissue in anatomic sites outside the uterine body. "In endometriosis, PEA technology identified seven proteins up-regulated (IL-6, IL-8, CCL 19, SCF, VEGF-D, IL-6RA, MIA9) and ten proteins down-regulated (ICOSLG, EGFR, SELE, ErbB2/HER2, IL-6RA, VEGFR-2, Flt3L, CXCL10, HE4, FR-alpha)." (PMID 36009404, 2022).
Hepatic steatosis (5 papers, 2019 to 2024). Steatosis is a term used to denote lipid accumulation within hepatocytes.
squamous cell carcinoma (5 papers, 2014 to 2022). A carcinoma arising from squamous epithelial cells. "In human squamous cell carcinomas and merkel cell carcinoma, inhibition of vascular E-selectin expression led to decreased leukocyte infiltration." (PMID 26943029, 2016). "When squamous cell carcinoma samples were treated with a toll-like-receptor-7 agonist, imiquimod, up-regulated tumor vessels E-selectin expression was found on previously E-selectin negative tumor-associated vessels." (PMID 35663420, 2022).
systemic sclerosis (5 papers, 2004 to 2023). A chronic disorder, possibly autoimmune, marked by excessive production of collagen which results in hardening and thickening of body tissues. "The serum level of SELE has been found significantly elevated in systemic sclerosis with early onset disease." (PMID 37849501, 2023).
arteriosclerosis (4 papers, 2020 to 2025). A vascular disorder characterized by thickening and hardening of the walls of the arteries. "Our present study found that coal-fired PM2.5 promoted E-selectin expression, indicating that PM2.5 may aggravate arteriosclerosis by inducing upregulation of E-selectin." (PMID 32384920, 2020).
bacteremia (4 papers, 2018 to 2022). "It has been noted that particular strains of S. aureus are able to induce the expression of selectins (E-selectin) and integrins (ICAM-1); in addition, a high level of E-selectin expression correlates with the severity and duration of bacteremia in patients infected with S. aureus." (PMID 36144298, 2022).
metastatic tumor (4 papers, 2008 to 2022). "We analyzed SELE expression in our patient cohort and observed significant downregulation of this gene in metastatic disease (localized mean = 3.381, metastatic mean = 0.881, p = 6 × 10–10)." (PMID 36371231, 2022).
scleroderma (4 papers, 2013 to 2024). Scleroderma is a rare autoimmune connective tissue disorder characterized by abnormal hardening of the skin and, sometimes, other organs. "At the same time, our pre-venular capillaries and post-capillary venules contain key upregulated genes like PLAUR and SELE, respectively, that were dissimilar to those seen in SSc, signifying localized scleroderma has independent signatures and pathways distinct from SSc." (PMID 39408800, 2024).
Autoimmunity (3 papers, 2011 to 2024). The occurrence of an immune reaction against the organism's own cells or tissues. "E-selectin, the protein encoded by SELE, is critical in recruiting leukocytes to sites of inflammation and damaged skin during chronic inflammation and autoimmunity." (PMID 39408800, 2024).
gouty arthritis (3 papers, 2013 to 2022). "Events involved in the onset of gouty arthritis were described as an initial leukocyte trafficking (neutrophils and mononuclear cells) accompanied by increased E-selectin expression (E-selectin is endothelial-leukocyte adhesion molecule that is expressed by endothelial cells activated by cytokines)." (PMID 36672554, 2022).
hyperlipidemia (3 papers, 2013 to 2023). "A clinical study on patients with hyperlipidemia reported that cardiotonic pills significantly decreased ICAM-1 and E-selectin expression." (PMID 37111353, 2023).